TET2 (tet methylcytosine dioxygenase 2)
Diseases named in the same sentence as TET2 in open-access papers (continued):
Sharing a sentence is not in itself a finding about the gene and the disease.
tumor (continued). "TET2 was up-regulated in oesophageal cancer in comparison with normal epithelium, suggesting an oncogenic role for this gene and, conversely, TET1 seems to behave as a tumour-suppressor gene." (PMID 32429269, 2020). "We found that, in concordance with the results observed in our TET2 KO models and in contrast to our observations in the TCGA dataset, methylation of the ASB2 promoter region was significantly increased in tumor samples as compared to normal (p = 0.04067, paired Wilcoxon signed-rank test)." (PMID 30917865, 2019). "We conclude that the MYC oncogene upregulates TET1 while suppressing TET2 expression in T-ALL, and speculated whether TET function was essential for tumor maintenance." (PMID 31266538, 2019). "We found that TET1 mRNA but not TET2 or TET3 was significantly reduced in tumor tissues compared with non-tumor tissues (P = 0.02, P = 0.55, and P = 0.21 respectively)." (PMID 31399111, 2019). "Also, in several tumor samples, consecutive sections were used for staining because the three antibodies specific for 5hmC, TET1 and TET2 shared the same host and hence double immunofluorescent staining was not possible to perform." (PMID 30045709, 2018). "All three up-regulated genes (CHD2, TET2, TNFAIP3) were annotated as tumor suppressors." (PMID 30425966, 2018). "While TET2 mutations have been described in ATLL patients, their direct impact on genomic 5-hmc in tumor cells was not evaluated." (PMID 28881727, 2017). "Moreover, the overexpression of the TET2 C-terminal domain partially suppressed the TGF-β1-induced EMT-like process in vitro and inhibited tumor growth and metastasis in vivo." (PMID 27852070, 2017). "In addition, the overexpression of the TET2 C-terminal sequence partially rescues the TGF-β1-induced EMT-like process in vitro and inhibits tumor growth and metastasis in vivo." (PMID 27852070, 2017). "We found that neither the rs72963007 nor the c.4045-1G > A TET2 variation resulted in 5-hmc reduction in ATLL tumor cells." (PMID 28881727, 2017). "TET1 mutations in hematopoietic malignancy have a much lower frequency than TET2 mutations and their deletions cause different tumor types, suggesting that TET1 and TET2 are non-redundant and lineage-specific." (PMID 26861406, 2016). "There were comparable expression of TET2 and TET3 in both of HCC tumors and non-tumor tissues." (PMID 23671639, 2013). "Together, these results imply a tumor suppressor role for TET1 and TET2." (PMID 24152442, 2013). "CAR-T cells containing the 4-1BB intracellular domain improved tumor treatment outcomes in mice after TET2 knockout, whereas CD28 signaling CAR-T cells exhibited no notable differences in cell differentiation or antitumor efficacy before versus after TET2 knockout." (PMID 40093905, 2025). "However, the hypoxia-induced DNA demethylation of the TWIST1 promoter or the SW480 genome appears to be independent of TET1 and TET2, which is in line with the fact that tumor hypoxia would reduce the TET enzymatic activity." (PMID 40764968, 2025). "Results revealed that repeated stimulation with CD19+ tumor cells allowed continual expansion of TET2 knockdown CAR T‐cells in an antigen‐dependent manner, whereas this same re‐stimulation in CAR T‐cells with wildtype TET2 resulted in complete arrest of cell growth." (PMID 40116537, 2025). "SDHA encodes a mitochondrial enzyme; its amplification may alter cellular metabolism through changes in succinate and α-ketoglutarate levels, potentially influencing the activity of epigenetic regulators such as TET2 and ASXL1, and immune modulation within the tumor microenvironment." (PMID 41373665, 2025). "Importantly, expression of these antigen presentation genes was relatively low in TET2-KO tumor cells regardless of VC treatment." (PMID 39388288, 2024). "Moreover, VC treatment also increased OT-I T cell killing in the WT B16-OVA coculture system, but not the TET2-KO group, as quantified by live tumor cell counts." (PMID 39388288, 2024).
tumor (continued). "Moreover, VC therapy did not exert a significant impact on tumor vessel coverage by pericytes, intratumoral hypoxia levels, and CD8+ T cell infiltration in these tumors with Tet2 or Stat5a deficiency." (PMID 38177099, 2024). "Similarly, the expression of TAP2, TAPBP, PSMB8, and B2M was each shown to be induced by VC treatment in the WT, but not TET2-KO, tumor cells." (PMID 39388288, 2024). "Two of the genomic alterations found enriched in older patient tumors may be attributed to age-related clonal hematopoiesis (DNMT3A, TET2), which may or may not be relevant to the actual tumor biology." (PMID 38975340, 2024). "However, while the disruption of TET2 improves CAR T cell therapy, its use as a therapeutic strategy may be limited because TET2 is a tumor suppressor." (PMID 37467321, 2023). "Furthermore, TET2 (in combination with either TET1 or TET3) dampens regulatory T cell immunosuppressive function, which are a critical cellular subset known to suppress anti-tumor responses." (PMID 37841428, 2023). "Moreover, five writers (NOP2, NSUN2, NSUN3, NSUN4 and NSUN5), one reader (ALYREF) and two erasers (TET2 and TET3) were consistently upregulated in UCB tumor tissues compared to adjacent normal tissues from TCGA cohort (fold change > 1.1, P-value <0.05, occurrence rate > 50%)." (PMID 36806253, 2023). "Likewise, HDAC inhibitors panobinostat, SAHA, and sulforaphane promote the generation of T cells with a central memory phenotype and reduce expression of immunosuppressive markers (PD-1, CTLA-4, TET2) in CAR T-cell, resulting in enhanced anti-tumor response in solid tumor models." (PMID 37153607, 2023). "Furthermore, mouse studies have shown that TET2 reshapes chromatin accessibility at genomic binding regions of key transcription factors involved in immune signaling (e.g., BATF and ETS1) favoring disfunction of tumor infiltrating lymphocytes (TIL)." (PMID 35237302, 2022). "Furthermore, CD8+ T-cell infiltration was not correlated with TET2 in OV, UCEC, and UCS, whereas tumor-associated fibroblast infiltration was significantly correlated with TET2 in BRCA, CESC, and OV." (PMID 35223782, 2022). "However, we observed that the expression change of TET enzymes in tumor tissue and cell lines is different, and TET2 is down-regulated in cell lines of GU cancers but not in the tumor tissues." (PMID 36127710, 2022). "First, the “writer” genes NSUN1-NSUN7, the “eraser” genes TET2 and ALKBH1, and the “reader” genes ALYREF and YBX1 were significantly upregulated or downregulated in tumor tissues, suggesting these genes may be critical in m5C-related occurrence and progression of COAD." (PMID 35281843, 2022). "In tumor models, inhibition of Tet2 in immune cells enhances antitumor immunity by reducing the functional immunosuppressive role of tumor-infiltrating myeloid cells (including MDSCs and TAM) and enhancing the tumor-killing activity of tumor-infiltrating lymphocytes (TILs)." (PMID 36203205, 2022). "Furthermore, the total TET2 protein levels were not available in the CPTAC database, and differences in TET2 phosphorylation levels were observed between normal and primary tumor tissues." (PMID 35223782, 2022). "However, in many other studies, TET2 mutation status did not affect responsiveness to HMT in patients with MDS and other related neoplasms." (PMID 34449560, 2021). "One study demonstrated that TET2 depletion could reduce Th1-type chemokines and PD-L1 expression by mediating the IFN-γ/JAK/STAT pathway, thereby decreasing tumor-infiltrating lymphocytes such as CD3+ and CD8+ T cell, and eventually it could compromise the efficacy of anti-PD-1/PD-L1 immunotherapy." (PMID 34957093, 2021). "Therefore, TET2 and EZH2 play a tumor-inhibiting role in AML that affects CIN via MAD2 and CDC20." (PMID 32066746, 2020). "This suggests that TET2 has roles as a tumor suppressor independent of its catalytic function." (PMID 33520997, 2020).
tumor (continued). "Explanted allografts with TET2 KO MSCs were significantly smaller and histologically revealed significantly less cells with a CAF phenotype, on staining with aSMA (ACTA1), thus demonstrating less efficient CAF conversion and tumor supporting capabilities in vivo." (PMID 31663852, 2019). "Using the χ2 test, consistent with TET2's main role being further oxidation of 5hmC, we saw a significantly greater frequency of SNVs/indels in Tet2−/− tumours at loci with 5hmC peak gains compared to loci with no change in 5hmC/5mC peaks and loci with 5hmC peak loss or 5mC peak gain." (PMID 28440315, 2017). "Therefore, we do not rule out the possibility that TET2 gene interacts with miRNA to achieve the function of tumor suppressor function." (PMID 29029424, 2017). "However, neither the amount of genomic 5-hmc in ATLL tumor cells nor TET2 expression has been studied yet." (PMID 28881727, 2017). "Although TET2 mRNA expression positively correlated to ARL4C mRNA expression and the expression of TETs mRNA inversely correlated to ARL4C DNA hypomethylation both in the 3’-UTR and promoter region, TET2 mRNA expression in tumor lesions was similar to non-tumor regions." (PMID 27835592, 2016). "In addition, the TCGA dataset revealed that the function of TET2 might be important to induce ARL4C gene expression in lung SCC, but whether elevated TET2 expression in tumor lesions is required for the expression of ARL4C remains to be clarified." (PMID 27835592, 2016). "In tumor cluster 2, antigen presentation processes were not identified among the top 20 enriched pathways, supporting the hypothesis that the increased antigen presentation pathways induced by VC in tumor cells was TET2 dependent." (PMID 39388288, 2024). "Interestingly, among TET family members, tumor suppressor TET2 expression was most positively correlated with cGAS expression and no negative correlation between tumor cGAS expression and DNA methyltransferases (DNMTs) was observed in HCC from TCGA and ICGC datasets." (PMID 38177099, 2024). "In addition, when crossing Tet1+/− mice with the SmoA1 mouse model, which has a high incidence of spontaneous MB development, we found a dramatic decrease in tumor incidence and tumor onset while the abolishment of Tet2 did not change tumor incidence and age-of-onset." (PMID 33926529, 2021). "Research has shown that TET1 is mainly expressed abnormally in solid tumours and can regulate the expression of oncogenes through DNA demethylation, while TET2 and TET3 play a role in regulating oncogenes and tumour suppressor genes in nonsolid tumours." (PMID 39823268, 2025). "While the absence of TET2 in MYC-driven tumors does not automatically mean it reinforces the tumor state, our ectopic TET2 expression experiments indicate a role as tumor suppressor." (PMID 31266538, 2019). "Our data applying qPCR, immunofluorescence, and Western blotting clearly show that TET2 and TET3 but not TET1 were significantly decreased in HCC tissue and different HCC cell lines compared to non-tumor liver tissues and hHeps." (PMID 26366235, 2015). "Consistently, deletion of TET2, but not TET1 or TET3, also increases the size of tumor cells." (PMID 37550284, 2023). "However, NSUN6, TET1, TET2, and TET3 did not have significant differences in tumor vs. normal tissues." (PMID 37907576, 2023). "However, when taking into account the increased miR-92a-5p expression in the cell lines, NHL tumour tissue, and increased miR-92a-3p expression in the Mino cell line compared to controls, it is suggestive that miR-92a-5p and −3p may not be strong negative regulators of TET2 within these subtypes." (PMID 34899857, 2021). "Interestingly, we found that TET2 and TET3 were significantly higher in the tumor tissues compared with normal tissues, but not TET1." (PMID 29983831, 2018).
tumor (continued). "These co-expression patterns based on primary tumor data are well-preserved in GSCs for TET2, but not for TET1 and TET3, strongly suggesting that TET2 is involved in regulating cell-cycle control and DNA damage repair, functions that have been previously linked to TET2 and 5hmC." (PMID 29587824, 2018). "Notably, ectopic expression of D2HGDH which partially reduces D-2-HG, does not change histone methylation markers and TET2-induced 5 hmC production in HT1080 cells, yet D2HGDH overexpression effectively inhibits the anchorage independent growth and tumor growth of these cells." (PMID 25825982, 2015).
cancer (294 papers, 2010 to 2026). A tumor composed of atypical neoplastic, often pleomorphic cells that invade other tissues. "The TET2 gene often undergoes mutations in malignant tumours and solid cancers of the hematopoietic system and is one of the most common mutated genes in clonal hematopoiesis in the general population." (PMID 41169875, 2025). "Somatic TET2 mutations are reported in numerous solid human cancers, including those arising in the skin, lung, and prostate, although there is a paucity of data on their frequency in these settings compared to hematological malignancies." (PMID 40116537, 2025). "Somatic TET2 mutations are reported in numerous solid human cancers, including those arising in the skin, lung and prostate." (PMID 40116537, 2025). "Rare lowfrequency constitutional variants in TET2 have also been investigated as risk factors for human cancer." (PMID 40116537, 2025). "Deletion of the DNMT1 gene rendered cancer cells susceptible to TET2 upregulation following exposure to DNMT inhibitors." (PMID 40675967, 2025). "Among these, TET2 has emerged as a gene of particular interest, as it is frequently mutated in various cancers." (PMID 40665337, 2025). "There is also evidence to suggest that somatic TET2 mutations affect prognosis in solid human cancers." (PMID 40116537, 2025). "TET2 has been extensively investigated for its role in epigenetics and its association with various cancers." (PMID 40665337, 2025). "The caging group as a transient active-site inhibitor canbe subsequently removed using light-induced deprotection, thus providinga means to gain precise insights into the effects of cancer-associatedmutations in TET2 on the catalytic kinetics of TET2 in vivo." (PMID 39737807, 2025). "TET2 is a tumour suppressor gene linked to various cancers, including haematological malignancies and solid tumours." (PMID 41015991, 2025). "The clonally unrelated RT, RT-1 which harbors a GC phenotype, showed the presence of MYD88, a CLL driver mutation, as well as mutations in genes implicated in cancer pathogenesis, TET2 and KMT2D, which have also been seen in RT." (PMID 39246801, 2024). "Tet2 is more active in stem cells during their differentiation, and cancers and other pathologies involve TET2 overproduction-related mutations." (PMID 39684407, 2024). "Simultaneously, TET2 mutations occur in human solid tumors, and a reduced TET2 protein expression is prevalent in several types of cancers." (PMID 38246976, 2024). "Among them, TET2 is unique in that it distinctly exhibits high mutation ratios in myeloid malignancies, with frequent IDH mutations observed in human cancers also thought to mainly act through TET2 inhibition." (PMID 39358506, 2024). "Changes in DNA methylation are a hallmark of cancer and were found in HSCs harboring CH mutations, including mouse models of Dnmt3a−/−, Dnmt3aR878H/+, Tet2−/−, Tet2+/−, and Asxl1." (PMID 39123361, 2024). "In patients with haematopoietic diseases, including cancer, mutation of ten-eleven translocation methylcytosine dioxygenase 2 (TET2) is one of the most commonly observed genetic abnormalities." (PMID 37620362, 2023). "To identify the overall landscape of TET2 malfunction, we examined the mutation and expression of TET2 in cancers originating from different organs in the TCGA database." (PMID 37620362, 2023). "TET1 and TET3 on the other hand are implicated in different cancers to a lesser extent – potentially due to their limited expression in adulthood relative to TET2." (PMID 36989121, 2023). "Ten-eleven translocation 2 (TET2) was found to be the target of cancer cell-secreted miR-210 in CAFs, which has been implicated in the pro-angiogenic switch." (PMID 36793444, 2023). "In terms of m5C modifications, the results showed that all the investigated cancers except OV were negatively associated with the eraser gene TET2." (PMID 36923798, 2023).